BAP1 (BRCA1 associated deubiquitinase 1)
Diseases named in the same sentence as BAP1 in open-access papers (continued):
Sharing a sentence is not in itself a finding about the gene and the disease.
leukemia (10 papers, 2018 to 2025). A malignant (clonal) hematologic disorder, involving hematopoietic stem cells and characterized by the presence of primitive or atypical myeloid or lymphoid cells in the bone marrow and the blood. "For instance, hyper-activation of BAP1 induced by ASXL1 gain-of-function mutations has been demonstrated to be drivers in leukemia of an animal model." (PMID 35194152, 2022). "This BAP1-induced mobility shift was also observed when we used the other leukemia-associated ASXL1 mutations [(c.1934dupG; G646WfsX12 and c.1772dupA; Y591X)]." (PMID 30013160, 2018). "*BAP1deubiquitinates the cell cycle regulator HCF‐1 and its binding partner OGT1 to suppress proliferation and cell cycle progression, limiting myeloid transformation. *Mutant ASXL1‐MT/BAP1 complex promotes leukaemia transformation." (PMID 39108012, 2024). "Our previous studies have shown that leukemia-specific C-terminus truncated ASXL1 is able to stabilize BAP1 and enhance BAP1’s recruitment to chromatin which promotes the expression of a pro-leukemic transcriptional signature." (PMID 36180891, 2022). "Taken together, these findings suggest that C-terminally truncated mutant ASXL1 proteins are highly expressed in leukemia cells and impair the association of wild-type ASXL1 with BAP1 in a dominant-negative manner." (PMID 32683582, 2021). "BAP1 is also required for the growth of MLL-fusion leukemia cells through the upregulation of HOXA gene expression." (PMID 30013160, 2018). "We first examined the interaction between a leukemia-associated ASXL1 mutant [ASXL1 (1900–1922del; E635RfsX1517, which here we refer to as ASXL1-MT)] and BAP1 in 293T cells." (PMID 30013160, 2018). "Coexpression of ASXL1-MT and BAP1 promoted RUNX1-ETO9a-induced leukemia progression with higher efficiencies than did ASXL1-MT alone." (PMID 30013160, 2018). "Similar to our results using cSAM cells, Bap1 depletion profoundly inhibited the colonogenicity and leukaemogenicity of MLL-AF9 leukemia cells, and this effect was rescued by expression of exogeneous BAP1." (PMID 30013160, 2018). "To test this possibility, we assessed the role of Bap1 in MLL-fusion leukemia, a well-known AML subtype characterized by Hox gene dysregulation." (PMID 30013160, 2018). "Furthermore, in mutant ASXL1-driven leukemia models, reducing BAP1’s catalytic activity has been shown to inhibit leukemia development and extend the survivability of animals." (PMID 35194152, 2022). "Bap1 depletion resulted in a profound reduction in the numbers and sizes of cSAM cell colonies, and also delayed the development of leukemia in mice, suggesting an important role for Bap1 in ASXL1-MT-induced leukaemogenesis." (PMID 30013160, 2018). "Furthermore, BAP1 is also required for the growth of MLL-fusion leukemia cells with posterior HOXA gene dysregulation." (PMID 30013160, 2018). "In addition, C-terminally truncated ASXL1 can be detected in leukemia cells with an ASXL1 mutation and expression of ASXL1 with a C-terminal truncation may confer a gain-of-function by promoting BAP1 activity." (PMID 33483612, 2021). "Such displacement is dependent on BAP1 catalytic activity, in agreement with the requirement of ASXL1 for correct PRC2 activity at the HOX genes in leukemia." (PMID 34186021, 2021). "We then assessed the effect of coexpression of BAP1 and ASXL1-MT on the leukaemogenicity of RUNX1-ETO leukemia." (PMID 30013160, 2018). "We then transduced Cas9 and Bap1-targeting gRNAs (sgBap1 #1 and #2) into the MLL-AF9 cells, and examined the effect of BAP1 depletion in MLL-AF9 leukemia cells." (PMID 30013160, 2018). "Moreover, in leukaemia, USP10, USP9X, BRCC36, and BAP1 participate in chromosomal translocation or are inactivated by somatic mutations." (PMID 39108012, 2024).
nevus (10 papers, 2013 to 2026). Nevus (or naevus, plural nevi or naevi, from nævus, Latin for "birthmark") is the medical term for sharply circumscribed[1] and chronic lesions of the skin or mucosa. "The biopsy of the right shoulder papule demonstrated a combined melanocytic nevus, consisting of a conventional nevus component and epithelioid melanocytes with loss of BAP1 expression by IHC." (PMID 41551629, 2026). "However there is some overlap in tumor biology as ~80% of blue nevi, which are benign melanocytic tumors of the skin, also harbor GNAQ or GNA11 mutations, and BAP1 mutations can be found in both cutaneous nevi and cutaneous melanoma." (PMID 23694694, 2013). "Given the histologic and immunohistochemical features, this lesion was classified as a BAP-1 inactivated nevus (“BAPoma”)." (PMID 35052351, 2021). "Immunohistochemistry (IHC) showed BAP1 expression in small nevus cells but deficient or absent BAP1 expression in the larger epithelioid melanocytes." (PMID 41551629, 2026). "On histologic examination, all 15 cases with ≥2 CNAs showed a nodular or dome‐shaped lesion; the architecture was symmetric in 10/15 cases, with definitive background BAP1‐retained nevus present in 7/15 and not identified in 8/15 cases." (PMID 39976080, 2025).
ocular melanoma (10 papers, 2012 to 2023). A melanoma that arises from the structures of the eye or ocular adnexa. "In conclusion, based on our molecular findings, CM comprises a separate entity within the ocular melanoma group, although there certainly are overlapping molecular features with UM, such as the presence of BAP1 and SF3B1 mutations." (PMID 34071371, 2021). "BAP1 has been shown to be a target of both somatic alteration in high-risk ocular melanomas (OM) and germline inactivation in a few individuals from cancer-prone families." (PMID 22545102, 2012). "Therefore, germline BAP1 inactivation appears to contribute to metastatic risk in a small, but significant, proportion of ocular melanoma cases." (PMID 22545102, 2012). "Lastly, BAP1 mutations occur with greater frequency among metastatic ocular melanoma (OM) patients compared to their non-metastatic OM counterparts." (PMID 34442055, 2021).
thymic carcinoma (10 papers, 2022 to 2025). Thymic carcinoma (TC) is a type of thymic epithelial neoplasm characterized by a high malignant potential. "In thymic carcinomas, mutations were found in genes involved in the histone modification pathway, including BAP1 (6%), SETD2 (11%), ASXL1 (4%), and in chromatin remodeling genes, such as SMARCA4 (4%)." (PMID 38201593, 2023). "The presence of BAP1 mutations serves as a predictive factor for resistance to immunotherapy in thymic carcinomas." (PMID 38201593, 2023). "Loss of BAP1 occurred in four (of 35, 11.4%) thymic carcinomas, including mucoepidermoid carcinoma, undifferentiated carcinoma, adenocarcinoma, and squamous cell carcinoma (n = 1, each)." (PMID 35565429, 2022). "BAP1 mutations are associated with low PD-L1 expression in thymic carcinoma." (PMID 38201593, 2023). "A large subset of thymic carcinomas (88.9%) could be predicted using a combination of loss of BAP1 and/or mTAP expression and/or expression of CD117 in ≥10% of tumor cells." (PMID 35565429, 2022). "In addition, pathogenic genomic alterations of BAP1 have been identified in 8.2% of thymic carcinomas." (PMID 35565429, 2022). "Therefore, loss of expression of BAP1 may help to distinguish thymomas from thymic carcinomas even though only a small percentage of thymic carcinomas would be recognized with that marker." (PMID 35565429, 2022). "CD5, CD117, EZH2, POU2F3, MTAP, and BAP1 have been proposed as useful markers for the distinction of thymic carcinoma from thymoma." (PMID 40242668, 2025). "A trend for the absence of co-occurrence with GTF2I was observed also for CDKN2A, BAP1, CYLD, and KIT mutations, which are genes frequently mutated in B3 thymomas and thymic carcinomas." (PMID 37671056, 2023). "We recently showed that a panel of CD117, BAP1, mTAP, and TdT was able to predict 89% of thymic carcinomas and 78% of type A and B3 thymomas and MNTLS, leaving room for improvement in immunohistochemical panels for this differential diagnosis." (PMID 37190202, 2023). "Loss of BAP1 and MTAP1 immunoreactivity was 100% specific for thymic carcinoma versus thymoma and occurred in 11% (4/36) and 14% (5/35) of the evaluable carcinomas, respectively." (PMID 37190202, 2023). "We found that a panel of CD117 with a cut-off of 10% tumor cell expression, BAP1, mTAP, and TdT was able to predict 88.9% of thymic carcinomas and 77.8% of thymomas (among the studied types A and B3 thymomas and micronodular thymomas with lymphoid stroma)." (PMID 35565429, 2022). "None of the thymic carcinomas showed loss of either marker except for one adenocarcinoma in which tumor cells showed loss of expression of BAP1 and a subset of tumor cells also showed loss of expression of mTAP." (PMID 35565429, 2022). "Loss of expression of BAP1 and mTAP was observed in a subset of thymic carcinomas but not in thymomas." (PMID 35565429, 2022). "We explored the relationship between CD5, CD117, EZH2, POU2F3, MTAP, and BAP1 immunoreactivity and the overall survival (OS) and progression-free survival (PFS) of patients with thymic carcinoma, using a cohort with diverse histologic subtypes." (PMID 40242668, 2025). "We aimed to determine the prognostic significance of CD5, CD117, EZH2, POU2F3, BAP1, and MTAP immunohistochemical staining in thymic carcinomas." (PMID 40242668, 2025).
thymic carcinoma (continued). "Recently, researchers of the Mayo Clinic (Rochester, MN, USA) used a panel of CD117, BAP1, mTAP and TdT in a series of 81 TETs including 44 thymomas and 37 thymic carcinomas and concluded that this panel could be useful to distinguish thymomas from thymic carcinomas." (PMID 37240815, 2023). "Our study showed that a panel of IHC markers, including BAP1, mTAP, CD117, and TdT can aid in predicting the vast majority of thymic carcinomas and epithelial cell-rich thymomas, including types A and B3 thymomas and MNTLS." (PMID 35565429, 2022). "In this series of 81 TET, including 37 thymic carcinomas and 44 thymomas (including type A and B3 thymomas and MNTLS) we have shown that a panel of CD117, BAP1, mTAP, and TdT can correctly predict 88.9% of thymic carcinomas and 77.8% of thymomas." (PMID 35565429, 2022). "Whole slide sections of 37 thymic carcinomas, 23 type A thymomas, 13 type B3 thymomas, and 8 micronodular thymomas with lymphoid stroma (MNTLS) were immunostained for EZH2, POU2F3, CD117, CD5, TdT, BAP1, and MTAP." (PMID 37190202, 2023). "In this study, we demonstrated that 11% of thymic carcinomas had lost nuclear expression of BAP1, a finding that we did not observe in any of the tested thymomas." (PMID 35565429, 2022). "Genes involved in histone modification (BAP1, 13%; SETD2, 11%; ASXL1, 4%), chromatin remodelling (SMARCA4, 4%), and DNA methylation (DNMT3A, 7%; TET2, 4%; WT1, 4%) were frequently mutated in thymic carcinomas, but not thymomas." (PMID 35884448, 2022). "Using BAP1, mTAP, CD117 (cut-off, 10%), and TdT, 88.9% of thymic carcinomas (95.7% of squamous cell carcinomas) and 77.8% of thymomas could be predicted." (PMID 35565429, 2022). "Overall, only 11.1% of thymic carcinomas and 22.2% of thymomas could not be predicted using a panel of BAP1, mTAP, CD117, and TdT." (PMID 35565429, 2022). "Furthermore, preserved expression of BAP1 did not exclude the possibility of thymic carcinoma." (PMID 35565429, 2022). "Expression of BAP1 and mTAP have not been studied in TET, but the molecular studies suggest that those markers could be useful in the distinction between thymomas and thymic carcinomas." (PMID 35565429, 2022).
familial melanoma (9 papers, 2020 to 2025). Familial melanoma (FM) is a rare inherited form of melanoma characterized by development of histologically confirmed melanoma in two first degrees relatives or more relatives in an affected family. "While PVs have also been detected in several other genes, including CDK4, BAP1, ATM, MITF and multiple telomere stability genes TERT, POT1, ACD, and TERF21P, about half of the cases of familial melanoma remain unexplained." (PMID 40072281, 2025).
myeloid malignancies (9 papers, 2018 to 2024). "Notably, deleting one Bap1 allele in these mice (i.e., Bap1Δ/+; Asxl1Y588XTg) partially restored H2AK119Ub1 occupancy at the promoters of these genes, normalized their expression, and prevented the development of myeloid malignancies." (PMID 36068610, 2022). "Germline BAP1 mutations are found in a spectrum of human malignancies, while ASXL1 mutations recurrently occur in myeloid neoplasm and are associated with poor prognosis." (PMID 32683582, 2021). "Hence, we propose that the predominance of ASXL mutations in myeloid malignancies may be the result of a selective pressure aimed at only partially ablating BAP1 function, whereas loss of BAP1 in other malignancies would reflect a need for complete inactivation of the complex." (PMID 30664650, 2019). "For example, our group recently demonstrated that frameshift mutations affecting the BAP1 complex subunit ASXL1 (which are frequently observed in myeloid malignancies) create truncated gain-of-function ASXL1 mutants that stabilize the BAP1 complex and increase its recruitment to chromatin." (PMID 39403928, 2024). "In addition, we reported that ASXL1 truncation mutations enhanced BAP1 deubiquitinase (DUB) activity, and that genetically reducing BAP1 in Asxl1Y588XTg mice prevented the development of myeloid malignancies." (PMID 36068610, 2022). "Therefore, reducing BAP1 levels and activity could prevent ASXL1 truncation-driven myeloid malignancies." (PMID 35194152, 2022). "In addition, BAP1 and USP16, both of which are H2AK119ub1 DUBs, have antitumor functions and are often absent or mutated in multiple solid tumors and myeloid malignancies." (PMID 34706761, 2021). "Inhibition of BAP1 activity, rather than enhancing it, may thus represent a promising therapeutic strategy for myeloid neoplasms involving posterior HOXA dysregulation." (PMID 30013160, 2018).
colon carcinoma (8 papers, 2015 to 2024). "We further investigated the mechanisms by which BAP1 supports the viability of colon cancer cells by focusing on HCT116 and SW48 cells, which exhibited the highest sensitivity to BAP1 deficiency among the eight cell lines analyzed." (PMID 36754982, 2023). "Our data also showed that BAP1 depletion inhibited colon cancer cell proliferation and tumor growth." (PMID 36754982, 2023). "First, TG2-179-1 treatment produces the same effects as BAP1 depletion in colon cancer cells: reduced replication fork progression, increased fork stalling, and increased apoptosis." (PMID 36754982, 2023). "Our data instead showed that BAP1 depletion suppressed replication fork progression with concomitant induction of replication stress and apoptosis, suggesting that BAP1 promotes colon cancer cell proliferation by increasing the rate of DNA replication." (PMID 36754982, 2023). "This work therefore reveals that BAP1 acts oncogenically in colon cancer and is a potential therapeutic target for this cancer and suggests that TG2-179-1 can be developed as a therapeutic agent for colon cancer." (PMID 36754982, 2023). "In this study, we showed that BAP1 is upregulated in colon cancer, with its expression significantly elevated in both cancer tissues and cancer cell lines compared to their normal counterparts." (PMID 36754982, 2023). "BAP1 contributes to colon cancer cell proliferation by accelerating DNA replication and suppressing replication stress and concomitant apoptosis." (PMID 36754982, 2023). "Having verified that TG2-179-1 inhibits BAP1, we investigated its impact on the viability of colon cancer cells." (PMID 36754982, 2023). "We showed that BAP1 is upregulated in colon cancer cells and tissues and that BAP1 depletion reduces colon cancer cell proliferation and tumor growth." (PMID 36754982, 2023). "The data suggest that TG2-179-1 kills colon cancer cells by targeting BAP1, reproducing the results of BAP1 depletion, i.e., increased apoptosis and defective replication." (PMID 36754982, 2023). "Here, we show that BAP1 is upregulated in colon cancer cells and tissues and that BAP1 depletion reduces colon cancer cell proliferation and tumor growth." (PMID 36754982, 2023). "To confirm the results of the colony formation assay and determine the mechanisms by which BAP1 activity supports colon cancer cell viability, we analyzed apoptosis by Annexin-V/PI double staining." (PMID 36754982, 2023). "Approximately 77% of the colon cancer tissues (83 of 108) but only 33% of the normal colon tissues (4 of 12) were scored as BAP1-positive." (PMID 36754982, 2023). "BAP1 depletion reduces colon cancer cell proliferation concomitant with increased apoptosis and defective DNA replication." (PMID 36754982, 2023). "Then, we compared BAP1 expression between normal colon cells and colon cancer cells by immunoblot analysis." (PMID 36754982, 2023). "All eight colon cancer cell lines analyzed exhibited markedly higher BAP1 levels than the two analyzed normal colon cell lines." (PMID 36754982, 2023). "Collectively, these results strongly suggest that BAP1 plays a tumor-promoting role in colon cancer." (PMID 36754982, 2023). "Immunohistochemical staining data from the Human Protein Atlas showed that 100% and 55% of examined colon cancer patients exhibited high and medium BAP1 expression levels, respectively, depending on the source of the antibodies used." (PMID 36754982, 2023). "We also suggest that a recently identified BAP1 inhibitor can be developed as a potential therapeutic agent for colon cancer." (PMID 36754982, 2023). "This work therefore shows that BAP1 acts oncogenically in colon cancer and is a potential therapeutic target for this cancer." (PMID 36754982, 2023). "The growth of the BAP1-depleted cells into tumors was greatly suppressed compared to that of control cells, showing that BAP1 is critical for the tumorigenic growth of colon cancer cells." (PMID 36754982, 2023).